GJA8 (gap junction protein alpha 8)
Description:
Structural component of eye lens gap junctions. Gap junctions are dodecameric channels that connect the cytoplasm of adjoining cells. They are formed by the docking of two hexameric hemichannels, one from each cell membrane (By similarity). Small molecules and ions diffuse from one cell to a neighboring cell via the central pore.
Synonyms: Cx50; CAE; CAE1; CTRCT1; CZP1; MP70
Tractability: Antibody: UniProt places it where antibodies can reach, with high confidence; its Gene Ontology location is reachable by antibodies, with high confidence; UniProt predicts a signal peptide or a membrane-spanning region.
Gene: Protein-coding gene on chromosome 1 (147,902,795 to 147,909,269, forward strand). Ensembl gene ENSG00000121634.
Subcellular location: Cell membrane; Cell junction, gap junction
Pathways (Reactome):
Vesicle-mediated transport: Gap junction assembly
Gene Ontology:
Molecular function: gap junction channel activity; protein binding
Biological process: gap junction-mediated intercellular transport; cell-cell signaling; cell communication; transmembrane transport
Cellular component: connexin complex; plasma membrane; gap junction
Genetic constraint (gnomAD): Loss-of-function variants: 16 observed, 18.63 expected, observed/expected ratio (o/e) 0.86, 90% interval 0.58 to 1.3. The upper end of that interval is the gene's LOEUF score, 1.3, which puts it in group 5 of 6, group 1 being the genes least tolerant of losing a copy. Missense variants: 607 observed, 583.84 expected, observed/expected ratio (o/e) 1.04, 90% interval 0.97 to 1.11. Synonymous variants: 304 observed, 255.14 expected, observed/expected ratio (o/e) 1.19, 90% interval 1.08 to 1.31.
Homologues: Orthologues: chimpanzee GJA8 (99% identical), macaque GJA8 (95% identical), dog GJA8 (89% identical), guinea pig GJA8 (89% identical), mouse Gja8 (89% identical), rat Gja8 (89% identical), rabbit GJA8 (88% identical), pig GJA8 (87% identical), tropical clawed frog gja8 (67% identical), zebrafish gja8a (63% identical), zebrafish gja8b (62% identical). Paralogues in human: GJA3 (41% identical), GJA5 (40% identical), GJA1 (36% identical), GJA9 (34% identical), GJA10 (33% identical), GJA4 (32% identical), GJC1 (29% identical), GJC2 (27% identical), GJB2 (26% identical), GJB1 (26% identical), GJB6 (26% identical), GJD2 (25% identical), and 8 more.
Diseases named in the same sentence as GJA8 in open-access papers:
GJA8 is named in the same sentence as 48 diseases in open-access papers, as found by Europe PMC text mining. Sharing a sentence is not in itself a finding about the gene and the disease. The quoted sentences say what the papers report.
cataract (63 papers, 2008 to 2026). Partial or complete opacity of the crystalline lens of one or both eyes that decreases visual acuity and eventually results in blindness. "GJA8 is a major gap junction protein in the vertebrate lens, and mutations in the gja8 gene cause cataracts in humans." (PMID 36982479, 2023). "In this study, we identified pathogenic and probably pathogenic variants in the GJA8 gene in five unrelated families of patients with congenital isolated cataracts." (PMID 37367076, 2023). "Mutations in GJA8 (gap junction protein alpha 8, also known as connexin 50) lead to autosomal recessive cataracts of various different phenotypes." (PMID 37034386, 2023). "Congenital cataracts caused by GJA8 and GJA3 gene mutations show a variety of phenotypes, including nuclear, perinuclear, zonular, punctiform, pulverulent, jellyfish-like, star-shaped, full moon, Y-sutural, balloon-like, lamellar, and triangular phenotypes." (PMID 35457072, 2022). "In summary, our study showed that knocking out GJA8 in rabbit via CRISPR/Cas9 system causes human-like cataracts." (PMID 26912477, 2016). "In agreement with other studies, our genetic and histology results showed that impaired GJA8 function caused microphthalmia, small lens size and cataracts." (PMID 26912477, 2016). "Missense and frame-shift mutations of the genes encoding Cx46 and Cx50 (GJA3 and GJA8) have been identified in members of human families with inherited cataracts of various different phenotypes." (PMID 24575044, 2014). "Several strains of mice or rats that develop cataracts also harbor mutations of the GJA3 (Cx46) or GJA8 (Cx50) genes." (PMID 25517998, 2014). "Mutations of the genes that encode these connexins (GJA3 and GJA8) have been identified and linked to inheritance of cataracts in human families and mouse lines." (PMID 23596416, 2013). "Previous studies have shown that other Gja8 mutations display phenotypic variations and the genetic backgrounds of mouse strains influence the severity of cataracts caused by connexin mutations." (PMID 23300808, 2012). "Most other GJA8 mutations associated with cataracts affect the transmembrane domains or the extracellular loops and are characterized by a dominant mode of inheritance." (PMID 18483562, 2008). "Mutations in the corresponding genes MIP/Mip, GJA3/Gja3, and GJA8/Gja8 (encoding the gap junction membrane channel protein α3 and α8, respectively) have been shown to underlie some congenital, mainly dominant cataracts in mouse and man." (PMID 18483562, 2008). "Differences in the expression patterns of Cx46 and Cx50 may be the reason that GJA3 gene mutations cause cataracts only, while GJA8-related cataracts are accompanied with microcornea or glaucoma in half of the reported cases." (PMID 35457072, 2022). "In this study, we investigated a four-generation family with congenital nuclear and zonular pulverulent cataracts and detected a novel missense mutation in the connexin 50 gap junction protein, alpha 8 (GJA8) gene that cosegregated with the disease in the family." (PMID 23592913, 2013). "Almost all point mutations in Gja3 and Gja8 lead to variable dominant cataracts in mice and humans." (PMID 23300808, 2012). "Murine Gja8 dominant as well as null mutations also display different types of cataracts." (PMID 21031021, 2010). "The same knock-in can rescue the cataracts caused by dominant form of mutant Gja8." (PMID 18470322, 2008). "L7Q is a novel mutation in connexin 50 (Gja8), causing semi-dominant pulverulent cataracts." (PMID 18470322, 2008). "Thus, Mutations in Gja8 (V353L) may cause disruption of lens homeostasis and are implicated in cataracts in ICR models." (PMID 37875594, 2023). "Disruption of either Cx46 or Cx50, encoded by Gja3 or Gja8 genes, abolishes intercellular gap junction communication to impair fiber-to-fiber coupling, which disrupts lens current circulation and homeostasis, leading to different types of cataracts and/or smaller lenses." (PMID 34465795, 2021).
cataract (continued). "In addition, sequencing of GJA3 and GJA8 genes in 41 congenital cataract probands revealed one known mutation in GJA3 gene inherited dominantly and two mutations in GJA8 gene (one novel and one known) segregating in an autosomal dominant fashion in cataract families." (PMID 29461512, 2018). "In the first model, demographic factors and the SNPs of the GJA8 gene were used to predict the age-related cataract, while in the second model the demographic factors and the haplotypes of the GJA8 gene were used for prediction age-related cataract." (PMID 37651414, 2023). "In this study, we investigated genetic variants in CRYAA, CRYAB, CRYGC, CRYGD, CRYBA1, GJA8, and GJA3 genes in 94 patients with congenital isolated cataracts from 45 unrelated families." (PMID 37367076, 2023). "Several genes have been associated with the presence of these two types of cataracts (CRYAA, CRYBA3/A1, CRYGC, CRYGD, CRYGS, connexin 46 [GJA3], and connexin 50 [GJA8])." (PMID 19390652, 2009). "Approximately 50% of cases may have a genetic cause, and GJA8 (encoding Cx50) and GJA3 (encoding Cx46) gene mutations account for about 20% of non-syndromic inherited cataract cases." (PMID 35457072, 2022). "Variations in phenotypic expression based on mutation location are clearly observed for the connexin gene (Cx50; GJA8), in which mutations may lead to pulverulent or jellyfish-like cataracts." (PMID 23288985, 2012). "As much as 70% of autosomal dominant cataract may be accounted for by missense coding mutations in the genes for crystallins, particularly CRYAA, CRYBB2, and CRYGD, and connexins (GJA3, GJA8)." (PMID 21042563, 2010). "Finally, variations in at least eight genes underlying genetic forms of cataract (EPHA2, GJA8, GALT, SLC16A12, HSF4, GALK1, FTL, and CRYAA), and at least 10 other diverse genes have been associated to varying degrees with age-related cataract." (PMID 21042563, 2010). "Disruption of either of the two connexin genes, connexin 46 (CX46, gap junction alpha 3 [GJA3]) and connexin 50 (CX50, GJA8), which are the major components of mammalian lens fiber cells, results in cataracts in mice." (PMID 23592915, 2013). "GJA3 and GJA8, but not GJA1, have been associated with cataracts in previous studies." (PMID 36009466, 2022).
congenital cataracts (28 papers, 2009 to 2025). "So, extensive research has been carried out to investigate the GJA8 gene and its polymorphisms in congenital cataracts, more research should be done to identify the role of the GJA8 gene in age-related cataracts." (PMID 37651414, 2023). "More than 60 pathogenic mutations have been identified in the GJA8 gene worldwide, making it a key player in the development of congenital cataracts." (PMID 37367076, 2023). "Mutations of the genes encoding Cx46 or Cx50 (Gja3 or Gja8) are linked to the development of congenital cataracts in people." (PMID 36171977, 2022). "This is the first time that FRMD7 and GJA8 gene mutations have been linked to the pathogenesis of a family with both CN and congenital cataracts." (PMID 30890130, 2019). "In this study, we identified a family with congenital cataracts associated with a variant of GJA8 encoding a substitution in the fourth transmembrane domain of Cx50 (c.658A>G; p.N220D) and examined the biochemical and functional consequences of this variant." (PMID 28827829, 2017). "Mutations in the GJA8 gene have been demonstrated to be one of the most frequent reasons for isolated congenital cataracts." (PMID 20019893, 2009). "However, several studies found that, in some congenital families with GJA8 mutations, the gap junction channel and hemichannel functions were only mildly impaired, which was insufficient to cause congenital cataracts." (PMID 30349978, 2018). "The GJA8 gene, which encodes Cx50, has been heavily investigated in congenital cataracts." (PMID 25517998, 2014). "The mutations of GJA3 (Cx46) and GJA8 (Cx50) are directly linked to human congenital cataracts." (PMID 22876138, 2012). "Moreover, GJA8 variants related to congenital cataracts could occur in any domain of the GJA8 protein." (PMID 30349978, 2018). "Because rabbits and humans are similar, the objective of this study was to create a novel animal model that recapitulated human congenital cataracts by using CRISPR/Cas9-mediated GJA8 gene knockout in rabbits." (PMID 26912477, 2016). "Increasing evidence over the last decade suggests that mutations in the Cx46 and Cx50 encoding genes, GJA3 and GJA8, respectively, are directly linked to human congenital cataracts in North and Central America, Europe and Asia." (PMID 24019978, 2013). "Among these, mutations in the GJA3 and GJA8 genes (that encode the lens gap junction proteins, CX46 and CX50) have been shown to underlie congenital cataracts, which most often exhibit dominant inheritance." (PMID 19756179, 2009). "Variants in gap junction protein alpha 8 (GJA8), the gene encoding connexin 50 (Cx50), are primarily associated with developmental cataract, although some are associated with severe structural eye anomalies, such as aphakia (absent lens), microphthalmia (small eyes), and sclerocornea." (PMID 40301690, 2025). "The gap junction protein alpha 8 (GJA8) gene has been widely studied in human congenital cataracts." (PMID 30349978, 2018). "The crystallin (CRYAA, CRYAB, CRYGC, CRYGD, and CRYBA1) and connexin (GJA8, GJA3) genes were analyzed in 45 unrelated families from the Volga–Ural Region (VUR) with hereditary congenital cataracts." (PMID 37367076, 2023).
nuclear cataract (16 papers, 2007 to 2025). A cataract (disease) that involves the lens nucleus. "The deletion of Gja3 results in recessive nuclear cataracts in mice, while a loss of Gja8 causes recessive phenotypes of small lenses and mild nuclear opacities." (PMID 23300808, 2012). "Previous studies showed that GJA8-knockout mice developed nuclear cataract and microphthalmia, from which it is considered that GJA8 plays a role not only in keeping lens transparent but in ocular growth." (PMID 21686328, 2011).
microphthalmia (12 papers, 2008 to 2025). Congenital or developmental anomaly in which the eyeballs are abnormally small. "This work provides molecular insights to understand the cataract and microphthalmia/microcornea phenotype caused by Gja8 mutations in mice and humans." (PMID 23300808, 2012). "We highlight that GJA8 variants represent an important source of genetic diagnoses not only for individuals with early onset cataract, but also for individuals with developmental eye anomalies, including microphthalmia and sclerocornea." (PMID 40301690, 2025). "In contrast to WT, GJA8 (+/−) rabbits showed opacity, smaller lens and obvious microphthalmia." (PMID 26912477, 2016).
Age-related cataract (6 papers, 2011 to 2026). A type of cataract (opacification of the lens) that forms during the course of aging. "However, limited studies reported an association of GJA8 gene variants with age-related cataracts." (PMID 37651414, 2023). "At least 8 genes are known to be directly associated with age-related cataracts, including EPHA2, GJA8, GALT, SLC16A12, HSF4, GALK1, FTL, and CRYAA." (PMID 36107580, 2022).
autosomal dominant congenital cataracts (5 papers, 2010 to 2023). "Both connexin 46 (Cx46) and connexin 50 (Cx50), which are encoded by the GJA3 and GJA8 genes, respectively, have been reported to be associated with autosomal dominant congenital cataracts." (PMID 25517998, 2014).
schizophrenia (4 papers, 2017 to 2025). A major psychotic disorder characterized by abnormalities in the perception or expression of reality. "Integrating accumulated priority data with known schizophrenia susceptibility genes, further analysis has identified GJA8 as a promising candidate gene for schizophrenia, supported by two independent pieces of evidence (from CNVs and genetic association or linkage studies)." (PMID 40792073, 2025). "Importantly, GJA5 and GJA8 are considered candidate genes for schizophrenia, largely due to their involvement in neural signaling and their location within the 1q21 chromosomal region, which is consistently linked to the disorder." (PMID 40792073, 2025).
glaucoma (2 papers, 2021 to 2022). Increased pressure in the eyeball due to obstruction of the outflow of aqueous humor. "In secondary childhood glaucoma cases, alterations in CYP1B1 (25%), SOX11 (13%), FOXC1 (13%), GJA8 (13%) and LTBP2 (13%) were detected." (PMID 35011756, 2021).
GJA8 also shares sentences with these, for which no sentence is quoted: aphakia (2 papers); autosomal dominant cataract (2); infection (2); Microcornea (2); Anterior polar cataract (1); Arrhythmia (1); benign pheochromocytomas (1); cardiomyopathy (1); Charcot-Marie-Tooth disease (1); congenital heart disease (1); congenital hypothyroidism (1); coralliform cataract (1); cortical cataract (1); dementia (1); diabetes (1); erythrokeratodermia variabilis (1); hearing loss (1); hyperlipidemia (1); Hypertension (1); ichthyosis (1); inherited diseases (1); Insulin resistance (1); keratitis (1); macular degeneration (1); malaria (1); malignant pheochromocytomas (1); metabolic disorder (1); metabolic syndrome (1); neuroblastoma (1); neurodegenerative disease (1).
A further 10 diseases each share a sentence with GJA8 in 1 paper.